RUNDC3A (RUN domain containing 3A)
Description:
May act as an effector of RAP2A in neuronal cells.
Synonyms: RPIP-8; RAP2IP; RPIP8
Tractability: PROTAC: its protein half-life has been measured.
Gene: Protein-coding gene on chromosome 17 (44,307,947 to 44,318,675, forward strand). Ensembl gene ENSG00000108309.
Subcellular location (Human Protein Atlas): Vesicles
Gene Ontology:
Molecular function: protein binding; GTPase regulator activity
Biological process: small GTPase-mediated signal transduction; cGMP metabolic process
Cellular component: cytosol; plasma membrane
Genetic constraint (gnomAD): Loss-of-function variants: 28 observed, 42.09 expected, observed/expected ratio (o/e) 0.67, 90% interval 0.49 to 0.91. The upper end of that interval is the gene's LOEUF score, 0.91, which puts it in group 3 of 6, group 1 being the genes least tolerant of losing a copy. Missense variants: 486 observed, 547.7 expected, observed/expected ratio (o/e) 0.89, 90% interval 0.82 to 0.96. Synonymous variants: 232 observed, 231.34 expected, observed/expected ratio (o/e) 1, 90% interval 0.9 to 1.12.
Homologues: Orthologues: chimpanzee RUNDC3A (100% identical), dog RUNDC3A (98% identical), macaque RUNDC3A (97% identical), mouse Rundc3a (96% identical), guinea pig RUNDC3A (92% identical), rat Rundc3a (87% identical), rabbit RUNDC3A (81% identical), tropical clawed frog rundc3a (79% identical), pig RUNDC3A (75% identical), zebrafish rundc3ab (70% identical), zebrafish rundc3aa (70% identical), Drosophila melanogaster CG31064 (21% identical), and 2 more. Paralogues in human: RUNDC3B (55% identical), RUFY1 (24% identical), RUFY3 (24% identical), RUFY2 (23% identical), SNX29 (20% identical), ZFYVE26 (19% identical), PLEKHM2 (17% identical), ZFYVE1 (12% identical), ZFYVE28 (12% identical), ZFYVE19 (11% identical), ZFYVE16 (9% identical), PLEKHF1 (8% identical), and 1 more.
Diseases named in the same sentence as RUNDC3A in open-access papers:
RUNDC3A is named in the same sentence as 14 diseases in open-access papers, as found by Europe PMC text mining. Sharing a sentence is not in itself a finding about the gene and the disease. The quoted sentences say what the papers report.
colorectal cancer (1 paper, 2024). A primary or metastatic malignant neoplasm that affects the colon or rectum. "The developed prognostic model and nomogram underscore the pivotal prognostic and regulatory significance of the lncRNA RUNDC3A − AS1 in the Warburg effect in colorectal cancer." (PMID 38685060, 2024). "In addition, we conducted colony formation assays to detect the colony formation ability of lncRNA RUNDC3A − AS1 in colorectal cancer." (PMID 38685060, 2024).
papillary thyroid carcinoma (1 paper, 2024). "RUNDC3A − AS1 exhibited significant differential expression in papillary thyroid carcinoma, playing a crucial role in cancer histotype determination." (PMID 38685060, 2024).
small cell lung carcinoma (1 paper, 2022). Small cell lung cancer (SCLC) is a highly aggressive malignant neoplasm, accounting for 10-15% of lung cancer cases, characterized byrapid growth, and early metastasis. "Further analysis of other types of NEC as well as small cell lung cancer, which resembles NEC on a molecular level, has identified RUNDC3A as an upstream molecule that regulates SNAP25 expression and the associated phenotypes that could enhance chemoresistance in NECs." (PMID 35752613, 2022).
tumor (3 papers, 2022). "Compared with the control group, RUNDC3A knockdown also significantly reduced the tumour growth rate as well as Ki67 staining in the GNEC xenograft model." (PMID 35752613, 2022). "Given their similar effect on tumor progression, RUNDC3A expression positively correlated with SNAP25 expression in GNEC patients." (PMID 36182960, 2022). "We further identified RUN domain containing 3A (RUNDC3A) as an upstream molecule that regulates SNAP25 expression, which is associated with tumor progression and chemoresistance in GNECs." (PMID 36182960, 2022). "Indeed, we validated that genetic depletion of RUNDC3A significantly reduced GNEC tumor growth both in vitro and in vivo." (PMID 36182960, 2022). "These three methylation sites could regulate the expression of corresponding genes (RUNDC3A, GRIK2, and KIF26B) that cause tumor growth and development, and therefore these sites might become new targets for tumor treatment." (PMID 35669882, 2022). "Collectively, our study demonstrated a novel mechanism in which overexpression of RUNDC3A and SNAP25 modulates Akt protein stability to enhance tumor growth and chemoresistance in GNEC." (PMID 36182960, 2022).
cancer (2 papers, 2022 to 2024). A tumor composed of atypical neoplastic, often pleomorphic cells that invade other tissues. "Overall, these results indicate that SNAP25 and RUNDC3A expression was coregulated in various cancer types." (PMID 35752613, 2022). "When the DEGs were further compared across four cancer types, we found five coregulated DEGs (upregulated DEGs: PCSK1N, CAMK2B, RUNDC3A and SNAP25; downregulated DEG: DPT) among four NECs." (PMID 35752613, 2022).
RUNDC3A also shares sentences with these, for which no sentence is quoted: amyotrophic lateral sclerosis (1 paper); frontotemporal dementia (1); gastric cancer (1); hepatocellular carcinoma (1); hereditary spastic paraplegia (1); lung carcinoma (1); metabolic disorder (1); neurodegenerative disease (1); Parkinson disease (1).